ENSG00000253060
Synonyms: LOC124900454
Gene: Small Cajal body-specific RNA gene on chromosome 1 (171,768,070 to 171,768,175, forward strand). Ensembl gene ENSG00000253060.
Gene Ontology:
Biological process: RNA processing
Cellular component: Cajal body; nucleolus